MMP23B (matrix metallopeptidase 23B)
Description:
Protease. May regulate the surface expression of some potassium channels by retaining them in the endoplasmic reticulum (By similarity).
Synonyms: MMP22; MIFR; MIFR-1
Tractability: Antibody: UniProt predicts a signal peptide or a membrane-spanning region; its Gene Ontology location is reachable by antibodies, with medium confidence.
Gene: Protein-coding gene on chromosome 1 (1,631,665 to 1,635,263, forward strand). Ensembl gene ENSG00000189409.
Subcellular location: Endoplasmic reticulum membrane; Membrane
Gene Ontology:
Molecular function: metalloendopeptidase activity; metallopeptidase activity; zinc ion binding
Biological process: collagen catabolic process; extracellular matrix organization; proteolysis
Cellular component: extracellular matrix; endoplasmic reticulum membrane; membrane
Genetic constraint (gnomAD): Loss-of-function variants: 4 observed, 2.83 expected, observed/expected ratio (o/e) 1.41, 90% interval 0.62 to 1.92. That is too few expected variants to judge how well the gene tolerates losing a copy. Missense variants: 129 observed, 54.09 expected, observed/expected ratio (o/e) 2.38. Synonymous variants: 71 observed, 31.17 expected, observed/expected ratio (o/e) 2.28.
Homologues: Orthologues: chimpanzee MMP23 (99% identical), macaque MMP23 (98% identical), pig MMP23B (91% identical), dog MMP23B (89% identical), mouse Mmp23 (84% identical), rat Mmp23 (80% identical), guinea pig MMP23B (79% identical), tropical clawed frog mmp23b (58% identical), zebrafish MMP23B (58% identical), Caenorhabditis elegans zmp-3 (23% identical), Caenorhabditis elegans zmp-4 (21% identical), Caenorhabditis elegans Y50D7A.13 (14% identical), and 2 more. Paralogues in human: MMP25 (29% identical), MMP11 (29% identical), MMP16 (29% identical), MMP14 (29% identical), MMP15 (29% identical), MMP2 (28% identical), MMP13 (28% identical), MMP17 (28% identical), MMP24 (28% identical), MMP8 (28% identical), MMP1 (28% identical), MMP20 (27% identical), and 11 more.
Diseases named in the same sentence as MMP23B in open-access papers:
MMP23B is named in the same sentence as 30 diseases in open-access papers, as found by Europe PMC text mining. Sharing a sentence is not in itself a finding about the gene and the disease. The quoted sentences say what the papers report.
breast carcinoma (4 papers, 2014 to 2024). "MMP23B (Matrix Metalloproteinase 23B) can promote the invasiveness of MDA-MB-231 breast cancer cells." (PMID 38782818, 2024). "As for the MMPs analyzed here, it was shown for MMP23B that it promotes cell invasiveness on MDA-MB−231 breast cancer cells." (PMID 32397602, 2020). "By MSRE-PCR, we identified abnormal hypermethylation of promoter CpG dinucleotides of five MMP genes, MMP2, MMP23B, MMP24, MMP25, and MMP28, in breast cancer." (PMID 32397602, 2020). "In our collection of 183 breast cancer samples, abnormal hypermethylation was observed for CpGs in MMP2, MMP23B, MMP24, MMP25, and MMP28 promoter regions." (PMID 32397602, 2020). "In fact, it has been shown that both MMP23B and TP73 are affected by hypermethylation of CpG sites in their promoter region, a mechanism that may activate breast cancer tumorigenesis." (PMID 33684137, 2021).
bladder cancer (3 papers, 2019 to 2025). "The expression and protein level of MMP23B (Matrix Metalloproteinase 23B) in blood and urine are associated with bladder cancer." (PMID 38782818, 2024). "The expression and protein levels of MMP23B (Matrix Metalloproteinase 23B) in blood and urine are associated with bladder cancer." (PMID 38782818, 2024). "Genes such as COL5A2, SVEP1, NID2, and MMP23B were responsible for the growth of many cancer types such as bladder cancer and mammary adenocarcinoma, but these genes may be involved in the pathogenesis of GBM." (PMID 31137733, 2019). "The MMPs with the highest correlation with GHR expression in both female and male patients with bladder cancer were MMP2 (rho = 0.472 (F), 0.457 (M)), MMP16 (rho = 0.464 (F), 0.509 (M)), and MMP23B (rho = 0.316 (F), 0.452 (M))." (PMID 40806252, 2025).
colorectal cancer (2 papers, 2015 to 2024). A primary or metastatic malignant neoplasm that affects the colon or rectum. "Upregulation of MMP23B (Matrix Metalloproteinase 23B) is significantly associated with higher tumor stages in colorectal cancer." (PMID 38782818, 2024).
COVID-19 (2 papers, 2021 to 2024). A disease caused by infection with severe acute respiratory syndrome coronavirus 2. "However, the human MMP family consists of several genes, and herein we show increased transcript levels of MMP-19, MMP-23B and MMP-25 in relation to disease severity in PBMC from COVID-19 patients, underscoring a role for MMPs beyond that of MMP-9 in COVID-19." (PMID 38957465, 2024). "Although matrix metallopeptidase (MMPs) are proteolytic enzymes responsible for extracellular matrix protein degradation, in our study matrix metalloproteases such as MMP23B, MMP15 and MMP14 were downregulated in COVID-19 diseased lungs compared with expression in lungs of uninfected controls." (PMID 33674719, 2021).
endometrial cancer (2 papers, 2010 to 2024). Primary or metastatic malignant neoplasm involving the endometrium (mucous membrane that lines the endometrial cavity). "We first conducted a CCK8 (Cell Counting Kit-8) experiment and found that after silencing MMP23B (Matrix Metalloproteinase 23B), its expression level decreased, leading to a decrease in the cell viability of endometrial cancer." (PMID 38782818, 2024). "The abnormal proliferation capacity of tumor cells is related to the enhancement of cell viability, indicating that low levels of MMP23B (Matrix Metalloproteinase 23B) reduce the proliferation capacity of endometrial cancer cells." (PMID 38782818, 2024). "The downregulation of MMP23B (Matrix Metalloproteinase 23B) reduced the cell viability of endometrial cancer cells, upregulated the expression levels of CASP3 (Caspase-3), CASP8 (Caspase-8) and CASP9 (Caspase-9) in cells, and inhibited cell migration and invasion." (PMID 38782818, 2024). "Moreover, our experiment also confirmed that downregulation of MMP23B (Matrix Metalloproteinase 23B) can inhibit the migration and invasion of endometrial cancer cells." (PMID 38782818, 2024). "In any case, our research indicates that MMP23B (Matrix Metalloproteinase 23B) is a potential therapeutic target for endometrial cancer, providing new ideas for the use of matrix metalloproteinase inhibitors in the treatment of endometrial cancer." (PMID 38782818, 2024). "MMP23B (Matrix Metalloproteinase 23B) was highly expressed in endometrial cancer, which is closely related to a poor survival prognosis for endometrial cancer, and may act on endometrial cancer through apoptosis-related functions." (PMID 38782818, 2024). "We believe that MMP23B (Matrix Metalloproteinase 23B) may be involved in the relevant regulation of the occurrence and development of endometrial cancer." (PMID 38782818, 2024). "The results showed high expression of MMP23B (Matrix Metalloproteinase 23B) in endometrial cancer." (PMID 38782818, 2024). "Therefore, we used cell biology and bioinformatics analysis to explore the role and possible mechanism of MMP23B (Matrix Metalloproteinase 23B) in endometrial cancer." (PMID 38782818, 2024). "Therefore, investigating whether the expression of MMP23B increases with tumor grading and whether it is also involved in the progression of endometrial cancer is with highly clinical value." (PMID 38782818, 2024). "Therefore, we decided to verify whether MMP23B (Matrix Metalloproteinase 23B) is involved in and regulates the proliferation and apoptosis signal transduction of endometrial cancer cells." (PMID 38782818, 2024). "At this point, we do not yet understand the function of MMP23B (Matrix Metalloproteinase 23B) in endometrial cancer." (PMID 38782818, 2024). "At this time, we downloaded important data on gene expression profiles and clinical data of endometrial cancer from the TCGA database (The Cancer Genome Atlas database) and analyzed factors such as MMP23B (Matrix Metalloproteinase 23B) that may be related to the prognosis of endometrial cancer." (PMID 38782818, 2024). "However, there is no report yet about the role and mechanism of MMP23B (Matrix Metalloproteinase 23B) in endometrial cancer." (PMID 38782818, 2024).
glioblastoma (1 paper, 2024). The most malignant astrocytic tumor (WHO grade IV). "The expression level of MMP23B (Matrix Metalloproteinase 23B) in primary glioblastoma patients is significantly higher in glioblastomas than in non-tumorous white matter." (PMID 38782818, 2024).
hyperplasia (1 paper, 2024). An abnormal increase in the number of cells in an organ or a tissue with consequent enlargement. "Further researches should be conducted on tissue samples from the patients to evaluate atypical endometrial hyperplasia and observe whether the expression of MMP23B has also changed in these tissues." (PMID 38782818, 2024).
pancreatic neuroendocrine tumor (1 paper, 2024). Pancreatic endocrine tumor, also known as pancreatic neuroendocrine tumor (PNET), describes a group of endocrine tumors originating in the pancreas that are usually indolent and benign, but may have the potential to be malignant. "Genes such as MMP23B (Matrix Metalloproteinase 23B) are related to immune infiltration in pancreatic neuroendocrine tumors." (PMID 38782818, 2024).
tumor (15 papers, 2013 to 2025). "In the clinicopathological analyses, upregulated MMP11, MMP14, MMP16, MMP17, MMP19, and MMP23B were significantly associated with a higher tumor stage." (PMID 34804973, 2021). "MMP11, MMP14, MMP16, MMP17, MMP19, and MMP23b were positively correlated with the tumor stage, that is, the mRNA levels of MMPs in patients with higher tumor stage were always high." (PMID 34804973, 2021). "In our study, abnormal hypermethylation of promoter CpG dinucleotides of the MMP2, MMP23B, MMP24, MMP25, and MMP28 was associated with HER2-positive tumor status, and, to a different extent, with CpG island hypermethylated epigenomic BC subtype." (PMID 32397602, 2020). "MMP23B expression is significantly different between tumor and para-tumor tissues in various cancers." (PMID 32432037, 2020). "MMP23 is a member of matrix metalloproteinase family (MMP23A, MMP21, MMP23B, MMP22) that participates in many aspects of tumour growth and metastasis." (PMID 26482227, 2015). "We found that MMP1, MMP3, MMP7, MMP9-MMP12, and MMP14 were significantly upregulated in tumor tissue, while MMP15–MMP17, MMP19–MMP21, MMP23A, MMP23B, and MMP25–MMP28 were significantly downregulated in tumor tissue." (PMID 34804973, 2021). "For example, we found that ATAD1, TBC1D9, and TNNC2 expression are all mediated by transcription factors ACTRT2, MMP23B, and TP73 and methylation sites around MMP23B and TP73; these transcription factors have known functions in tumor suppression or proliferation." (PMID 33684137, 2021). "Furthermore, cells in the myCAF-(F-POSTN) and iCAF-(F-ALPL) groups expressed high levels of matrix metalloproteinases (MMPs; e.g., MMP2, MMP14, MMP23B, and MMP19), indicating that these cells are involved in degradation of the basement membrane and ECM to facilitate tumor metastasis." (PMID 40319103, 2025).
cancer (12 papers, 2005 to 2025). A tumor composed of atypical neoplastic, often pleomorphic cells that invade other tissues. "MMP23B (Matrix Metalloproteinase 23B) has been less reported to be involved in cancer within this family." (PMID 38782818, 2024). "We here demonstrate that, though hypermethylation of certain CpGs in promoter regions of the MMP2, MMP23B, MMP24, MMP25, and MMP28 genes is cancer specific, it lacks independent biological or clinical value, being rather a function from HER2 activation." (PMID 32397602, 2020). "From various cancer formation and metastasis signals, it can be seen that a set of matrix metalloproteases (MMPs) (MMP27, MMP23B, THBS2, MMP13, MMP11) as well as the MMPs receptor ITGB3 were inhibited in GX0101-infected CEFs." (PMID 27200301, 2016). "Notably, downregulation of zebrafish orthologues for MMP23B, MMP28, and CTSF are consistent with downregulated expression of these genes in several human cancer types." (PMID 39511408, 2025). "Interestingly, MMP2, MMP7, MMP23B, MMP27 and MMP28) are significantly down-regulated in seven to nine cancer types." (PMID 31200666, 2019).
infection (1 paper, 2015). The state of being infected such as from the introduction of a foreign agent such as serum, vaccine, antigenic substance or organism. "It includes genes related to collagen production and organization (COL6A3, COL6A2, COL6A1, etc.), or matrix metalloproteinases (MMP) involved in extracellular matrix remodelling (MMP7, MMP23B), and previously implicated in infection response." (PMID 26331304, 2015).
MMP23B also shares sentences with these, for which no sentence is quoted: lung carcinoma (7 papers); melanoma (4); coronary heart disease (2); idiopathic pulmonary fibrosis (2); non-small cell lung carcinoma (2); prostate carcinoma (2); adenomyosis (1); atherosclerosis (1); cervical cancer (1); chronic obstructive pulmonary disease (1); hepatic carcinomas (1); ischemia (1); lymphoma (1); mammary adenocarcinoma (1); multiple myeloma (1); pancreatic cancer (1); prostate adenocarcinoma (1); schistosomiasis (1); synovial sarcoma (1).